IL10 (interleukin 10)
Diseases named in the same sentence as IL10 in open-access papers (continued):
Sharing a sentence is not in itself a finding about the gene and the disease.
infection (continued). "While all our mouse strains displayed an elevated total cell number in the draining lymph nodes already 3 days post infection, the increased footpad swelling of the T cell-specific and the complete IL-10-deficient mice was not detectable until 5 days post infection." (PMID 23825956, 2013). "Therefore, it was reasonable to presume that the low expression level of IL-10 in MPMs may contribute to a high inflammatory response, which may help mice to reduce the leptospiral burden during infection." (PMID 24130911, 2013). "In the present study, we genotyped SNPs of TNF, IFNG, IL6, IL10, and TGFB1 which are multifunctional cytokine that have been implicated in inflammation, immunity, and cellular organization and have been proposed to play important roles in infection and cancer biology." (PMID 23936772, 2013). "While the reason behind the differences in IL-10 levels in our study from previous studies remain to be explored, it is likely to reflect differences in both host and pathogen factors, including host and pathogen genotypes and presence of co-existent infections." (PMID 23544075, 2013). "Interestingly, the anti-inflammatory cytokine, IL-10 was secreted by ATII cells and MDM to significantly higher levels at 6 h post-BM infection compared to BP, then IL-10 levels decreased by 20 h post-infection, but remained higher than uninfected controls and BP-infected cells (p < 0.05)." (PMID 23293773, 2012). "Thus, while we now show that IL-27 secretion by APCs can be modulated through ligation of the PILRα and PILRβ receptors, we cannot eliminate the possibility that IL-10 may also contribute to the increased survival we observed after peroral infection." (PMID 22479310, 2012). "Interestingly, in the presence of robust IL-27 expression we also observed a greater induction of IL-10 in the serum of IL-27-expressing mice by day 7 post-infection compared to control or p28-expressing mice, while systemic IFNγ protein was similar between all groups." (PMID 22479310, 2012). "Interestingly, our lab found that Chinese highly pathogenic PRRSV (HP-PRRSV) infection failed to induce detectable IL-10 (unpublished data), but induced lower levels of TNF-α in PAMs." (PMID 22909062, 2012). "We hypothesize that timely interferon-regulated antiviral responses are critical determinants of outcome in primary infections, whereas inflammatory mediators and regulators of antibody-dependent enhancement, including IL-6, IL-8, and IL-10 may dominate in secondary infections." (PMID 23209847, 2012). "A number of stage-specific alterations in cytokine and chemokine response have also been described in CSF from HAT patients, and IL10 has been proposed as a potential diagnostic marker for infection and cure owing to the speed with which levels return to normal after treatment." (PMID 23145191, 2012). "Interestingly, Treg numbers increased in the colons of hfa mice during the course of C. jejuni-infection suggesting that production of IL-10 and other anti-inflammatory mediators might be involved in limiting C. jejuni-induced immunopathology." (PMID 21698299, 2011). "Thus, while one or more additional cell types may contribute to the pool of IL-10 observed during acute RSV infection, our results suggest that effector T-cells (both CD4+ and CD8+) may be a major source of IL-10 during human infection." (PMID 21829368, 2011). "This suggested that autologous IL-10 may be induced following cell infection." (PMID 21526166, 2011). "The STH infection effect (combined light and chronic infection groups) was associated with greater production of GM-CSF (P = 0.02) and IL-2 (P = 0.004) and the chronic STH infection effect with greater levels of GM-CSF (P = 0.007), IL-2 (P = 0.03), IL-5 (P = 0.01), and IL-10 (P = 0.01)." (PMID 21666788, 2011).
infection (continued). "Of note, our findings suggest that effector T cells are not only the major source of IL-10 in the infected lungs but may also serve as important cellular targets for the action of this regulatory cytokine, reflecting a novel autocrine pathway for the action of IL-10 during infection." (PMID 21829368, 2011). "As regard to this cytokine release, the concentration of IL-10 in the intestinal fluid was significantly decreased in the infected control group (S) throughout the study, while in mice from Lc-S group the significant decrease was observed 10 days post infection." (PMID 21813005, 2011). "Thus the immunosuppressive environment created by IL-10 in synergism with IL-6 may lead to the virus persistence or secondary infection, which may result in the more severe symptoms in the severe P(H1N1) patients." (PMID 22174866, 2011). "Therefore, early production of IL-10 after infection with Vi+Salmonella may be important in diminishing neutrophil influx and activation and thereby increasing the ability of this pathogen to efficiently colonise and infect distal sites within the host." (PMID 21829346, 2011). "Furthermore, this chronicity was not due to high levels of IL-10, as the level of infection was not greatly altered in mice deficient in this immunosuppressive cytokine." (PMID 21575914, 2011). "Interestingly, IL-10 showed a sustained induction from day 3 of infection." (PMID 21912714, 2011). "However, infection by the protozoan pathogens T. cruzi and L. mexicana elicited responses most similar to alternative activation by the Th2 cytokine IL-4 and to macrophage deactivation by the cytokine IL-10." (PMID 20361029, 2010). "Therefore, the endogenous production of IL-10 elicited by coinfection seems to be crucial to counterregulate the potentially lethal effects triggered by systemic release of pro-inflammatory mediators induced by CL Brener single infection." (PMID 20967289, 2010). "In all, our findings suggest that the major effects of IL-10 to suppress the immune response to Mtb are in the lung and dLN, and that by neutralizing this cytokine an earlier local Th1 response in the lung can dictate the subsequent level of protection observed up to 125 days of infection." (PMID 20518032, 2010). "However, the data reported here are more consistent with IL-10 production being a consequence of virulent infection rather than a cause of prolonged infection." (PMID 19860914, 2009). "chagasi infection in which curative type1responses may be suppressed by IL-10 and TGF-β." (PMID 19956549, 2009). "Moreover, our findings have important implications for the regulation of IL-10 production during an inflammatory Th1 response in infection and may be of relevance for the design of vaccines and for strategies in immunotherapy in infectious diseases." (PMID 19646904, 2009). "We speculate that IL-10 modulates MoDC function early after infection and, as a result, dictates the nature of the cytokine response induced early during antiviral immunity, favoring a Th2 cell/cytokine-like environment inducing FMDV specific neutralizing antibodies." (PMID 19478852, 2009). "However, significant reduction in the production of TNF, IFNγ, and IL10 were observed in SR-B1−/− mice following infection with a high dose of Mtb (1000 CFU/mouse), which marginally affected the size of inflammatory foci but did not influence bacterial burdens." (PMID 20041149, 2009). "Further work is now required to determine how these two key cell types (anti-parasitic effector T cells and IL-10-producing regulatory T cells) are induced, so that vaccines can be designed that will induce optimal numbers of each cell type at appropriate stages of the infection." (PMID 18401464, 2008). "However, the necessity of IL-10 in establishing T cell anergy is not complete in that LCMVClone13 established a persistent infection in IL-10 deficient mice, despite a robust early CD8 T cell response." (PMID 17570849, 2007).
infection (continued). "We speculate that infection of DCs with LCMVClone13 leads to IL-10 production by these cells directly or, alternatively, infected DCs could induce regulatory T cells that in turn would secrete IL-10." (PMID 17570849, 2007). "The relative expression of IL-6, IL-10, TNF-α, and IFN-α in the livers of infected mice significantly increased after BVDV infection, indicating that the infection triggers an inflammatory response in the host." (PMID 41514840, 2026). "Upon re-infection, healed PTX3-/- mice produced significantly more IL-17A, while levels of IFN-γ, TNF-α, and IL-10 were similar." (PMID 41743710, 2026). "aeruginosa infection, TSP-1 induces IL-10 in the lung tissue of mice inoculated with this bacterium." (PMID 41733356, 2026). "On day 3 post-infection, nasal administration of LGG before M. pneumoniae infection increased the anti-inflammatory cytokine IL-10." (PMID 41236498, 2026). "Levels of inflammatory cytokines IL‐1β, IL‐6, IL‐8, IL‐10, IL‐12/23p40, TNF‐α, and HMGB1 were significantly upregulated by infection with S. Typhimurium in the LT2 group." (PMID 41474380, 2026). "The abundance of Enterobacteriaceae or Escherichia-Shigella was positively correlated with rectal temperature at 12 and 24 h post-infection, serum TNF-α level, and jejunal IL-1β, IL-10, and TNF-α mRNA levels." (PMID 41547922, 2026). "In pre-infection samples (day 66), animals receiving the combination of live dpB and SARS-CoV-2 vaccination (group 4) showed statistically higher levels of IL-6 and IL-10, than inactivated dpB-SARS-CoV-2 vaccine group (group 2) (M-W, pb< 0.001; M-W, pb=0.040)." (PMID 40969767, 2025). "In the analysis of cytokines in the infected cecum, site of worm insertion, we observed a significant increase in IL-4, IL-10, TNF, and IFN-γ levels 10 days after infection." (PMID 39899646, 2025). "Bov342 infection resulted in upregulation of CXCL1, whereas VN1203 resulted in IFN-γ, IL-2, IL-5, and IL-10." (PMID 40410375, 2025). "Administration of anti-IL-10 to iron-loaded Tim3−/− animals or to splenocytes ex vivo restored IFNγ expression of CD4+ T cells and improved infection control under high iron conditions." (PMID 40939292, 2025). "For example, as infection progresses, the presence of IFN-γ in the bone marrow promotes the production of monocytes that produce IL-10 and PGE2 which contribute to the restoration of homeostasis." (PMID 39868131, 2025). "This is a similar trend to reports of NK cell IFN-γ and IL-10 production in vivo, which indicate that IL-10 initiates after an early IFN-γ response to infection." (PMID 40337867, 2025). "Following the infection of RAW264.7 cells with SFTSV at the MOI of 200 for 24 or 48 h, the levels of IL-1β, IL-6, IL-10, TNF-α, and MCP-1 were measured by using qPCR." (PMID 41472750, 2025). "Notably, IL-10 and β-catenin—both of which are associated with regulatory and anti-inflammatory functions—also exhibited altered expression, suggesting that SINV may modulate immune and survival pathways to influence infection outcome." (PMID 41157617, 2025). "Our study found that the early induction of IL-10 mRNA in SH-SY5Y neuroblastoma cells occurred following exposure to SINV, with transcript levels gradually declining over the course of the infection." (PMID 41157617, 2025). "In general, an increase in the RGE of the pro-inflammatory cytokines IFN-γ and TNF-α, as well as the anti-inflammatory cytokine IL-10, was observed in infected animals (IB1 and IB2) throughout the infection (Figs 2a1, 2c1, and 2e1)." (PMID 40743218, 2025). "Correlation analysis highlighted distinct immunological patterns, with IL-10 acting as a negative regulator of inflammation, while TNF-α and IL-17A reflected infection intensity depending on species and timing." (PMID 41156648, 2025). "We also measured inflammatory cytokine levels (TNF-α, IFN-γ, IL-1β, IL-6, IL-10, and IL-12) in the BALF supernatant 3 days post-infection." (PMID 39655914, 2025).
infection (continued). "The mRNA level of cytokines, including IL-1β, IL-10, IL-8, TNF-α, IFN-α, and IFN-γ, was detected in MARC-145si14-3-3γ and MARC-145siNC cells following infection with TA-12." (PMID 40704900, 2025). "HTLV-1A/CoI-L infection resulted in lower frequencies of all monocyte subsets producing IL-10+ in addition to those co-expressing CD162, over the course of the infection in both compartments." (PMID 41006234, 2025). "Infection with the wild-type strain led to increases in the levels of the inflammatory cytokines IL-6, TNF-α, and IL-10, but deletion of the porV locus significantly reduced the levels of these factors (P ≤ 0.01)." (PMID 40484959, 2025). "The tissue model mounted a strong inflammatory response to STm infection, as evidenced by the secretion of IL‐1β and TNF, while the anti‐inflammatory cytokine IL‐10 was also detected." (PMID 39807570, 2025). "These included interferons (IFN-α, IFN-β, and IFN-γ), proinflammatory factors (IL-1β, IL-6, and TNF-α), the anti-inflammatory cytokine (IL-10), and matrix metalloproteinases 3 (which contribute to blood-brain barrier disruption) after TMUV infection." (PMID 40401981, 2025). "In summary, TNF, IL-8, and IL-10 specifically increased following infection, whereas CCL2 and IL-18 showed an infection-dependent reduction." (PMID 40794782, 2025). "NC infection triggers a robust Th1-type immune response in cattle and dogs, mostly mediated by IFN-γ and IL-10 53,64." (PMID 41298714, 2025). "Elevated IL-10 levels can lead to reinfection or persistence of disease in the host, ultimately hindering PRRSV clearance and potentiating infection." (PMID 39943198, 2025). "The related bacterial species Bordetella bronchiseptica evades immune responses in infected mice by inducing IL‐10, which inhibits IFN‐γ production, resulting in prolonged infection of the lung." (PMID 40629997, 2025). "Several studies indicate an upregulation of myeloid differentiation primary response (MYD) 88-related signaling pathways upon infection of AlvMφ in vitro, leading to increased expression of cytokines (e.g., TNF-α, IL-1β, IL-8, IL-10) and chemokines." (PMID 39796262, 2025). "Cytokine profiling revealed elevated levels of TNF, IL-8, IL-10, and reduced levels of IL-18 and CCL2 in culture supernatants over the time of infection." (PMID 40794782, 2025). "This suggests that IL-10 is essential for supporting early erythroid differentiation and maintaining the function of EME during infection." (PMID 41471231, 2025). "The production of IFN-γ, TNF, and IL-10 was reduced in the draining lymph node, as well as the total number of CD3+CD4+IFN+ and CD3+CD4+TNF+ T cells in the infection site." (PMID 40982482, 2025). "Since our previous data demonstrated that ISG15 can induce IL-10 release, we monitored IL-10 production in the FGT tissues of mice following Ct infection." (PMID 40627782, 2025). "In agreement, after infection, the F3 vaccine determined the maximal IFN-γ/IL10 ratios (five- to eight-fold higher than the chimeras) and the most potent TNF-α/IL-10 ratios (eight- to 11-fold higher than the chimeras)." (PMID 40666521, 2025). "The high level of IL-6 probably induced IL-10 and VEGF-A expression for possible tissue repair at the initial and late stages of infection." (PMID 40358160, 2025). "Hence, the significant increase in tnf-α at 449 mg/kg (G2) might play a role in stimulating the immune system, which in turn mobilizes factors tgf-β and il-10 to respond positively against the impending inflammation, thus improving the body’s resistance to infection and immunity." (PMID 39858125, 2025). "The levels of IL-6, IL-10, and IFN-γ increased after infection, peaked at various time points, and then declined by 21 dpi." (PMID 41295722, 2025). "In infection with RSV, IL-10 can mitigate excessive inflammation and prevent severe immunopathology." (PMID 41156600, 2025).
infection (continued). "These lipid-laden macrophages secrete an anti-inflammatory cytokine profile (IL-10, TGF-β, CCL2) that establishes a chemotactic gradient, recruiting diverse immune cells and fibroblasts to infection sites." (PMID 40365535, 2025). "On the 10th and 14th DPI, the infection with T. evansi induced a significant upregulation of IL-1β and IL-6 mRNA expression levels, whereas mRNA expression levels of TGF-β and IL-10 were downregulated in all infected groups when compared to the CN group." (PMID 40571943, 2025). "The results indicated that 24 h post-infection (MOI 1:1), there was a significant increase in the production of TNF-α, IL-1β, and IL-10 compared to that in the control group." (PMID 40005637, 2025). "Infection of BALB/c and STS mice resulted in 10-500× increase of production of IFNγ IL-2, IL-4, IL-6 and IL-10 by their splenocytes, whereas strain O20 splenocytes did not produce any of these cytokines except IL-6." (PMID 41164189, 2025). "Together, these data show that different strains lead to different signatures of inflammatory responses in vivo, but that relative induction of MCP-1, IL-6, IL-10 and IFN-γ correlates with degree of virulence in a murine infection model." (PMID 40587585, 2025). "At 21 days post-infection, significant differences in IFN-γ and IL-10 levels persisted among the groups." (PMID 40446176, 2025). "IL-4 and IL-10 levels dramatically increased in the ITI and ITA infection group at 1 hpi, but significantly increased in the IN infection group at 3 hpi." (PMID 40723822, 2025). "Secreted CCL3, CCL4, CCL5, CXCL10, IFN-γ, IL-10, and VEGF were also significantly elevated in LCLs but at lower levels than in de novo infection." (PMID 40359016, 2025). "The control group displayed low expression of inflammatory cytokines, whereas infection significantly upregulated genes such as IL-1β, TNF-α, NF-κB p65, INF-γ, and IL-10 (p < 0.01)." (PMID 41030551, 2025). "In the mock infection group, however, the Winter PM exposure induced elevated IFN-γ, IL1-β, IL-8, IL-4, IL-5, IL-10, and VEGF-A at the 24 h timepoint." (PMID 40671793, 2025). "In lung tissue, IL1B, IL6, IL10, CXCL2, CCL3 and CCL5 levels also rose in both genotypes following infection, although these markers were significantly lower in TLR7 KO mice." (PMID 40442368, 2025). "SA infection also significantly decreased Arg1 expression (L2FC = −0.99, P = 0.0145) but increased Il10 expression (L2FC = 1.78, P = 0.0009)." (PMID 41025812, 2025). "Infection with GB112 resulted in elevated production of EGF, IL-1α, IL-10, sCD40L, and fractalkine in the maternal and fetal chambers of the organ-on-a-chip models, but not in the primary human gestational membranes." (PMID 41277827, 2025). "At later times in the course of infection, the cellular population showed induction of an inflammatory response, related to TNF and IL-10, and a transition to adaptive immunity with evidence of upregulation of genes involved in MHC-II presentation." (PMID 41600804, 2025). "Infection with T. spiralis led to a significant increase in arginase-1 and TNF-α gene expression, whereas the relative expression of IL-10 significantly decreased." (PMID 41239511, 2025). "In agreement with that, after infection by L. (V.)braziliensis, the chimeras also generated stronger IDR responses and secretions of IFN-γ, TNF-α, and IL-10, suggesting a regulatory profile." (PMID 40666521, 2025). "Levamisole and 25–100 mg/kg baicalin upregulated the mRNA expression of iNOS and CD86 and attenuated the levels of ARG1, IL-10, and CD163 in the spleen, in contrast with the infection group (p < 0.05)." (PMID 40427533, 2025). "S. Typhimurium induced the secretion of anti-inflammatory IL-10 and immunomodulatory IFN-β from siCtrl BMDMs 6 h after infection." (PMID 40276384, 2025). "Following VMV infection, BAL macrophage numbers are elevated and AlvMφ display an activated phenotype with secretion of IL-8, IL-6, IL-10, GM-CSF, TNF-α, IL-1β, and TGF-β." (PMID 39796262, 2025).